MTOR (mechanistic target of rapamycin kinase)
Diseases named in the same sentence as MTOR in open-access papers (continued):
Sharing a sentence is not in itself a finding about the gene and the disease.
tumor (continued). "Moreover, the activation of SREBP1 by mTOR promotes de novo lipid creation, which further accelerates tumor growth." (PMID 40428769, 2025). "Also, our study reveals crosstalk between HER2 and SMO: Combining trastuzumab with Hh inhibitors (Vis or Cyc) synergistically suppresses SMO, further inactivating AKT/mTOR signalling and enhancing anti-tumour effects." (PMID 40426308, 2025). "Inhibiting mTOR signaling may effectively eliminate CSCs, which are involved in tumor heterogeneity and contribute to drug resistance, metastasis, tumor formation, and recurrence." (PMID 40287470, 2025). "Conversely, several PTMs of HIF1α play tumor-suppressive roles, inhibiting BC progression and metastatic ability, reducing cell growth, inducing autophagy, or inhibiting different pathways involved in the malignant transformation of BC cells, such as mTOR." (PMID 39942749, 2025). "Besides frequent mutations in core components of this pathway (e.g., PIK3CA, PTEN, AKT), increasing evidence highlights ROS as critical modulators of PI3K/Akt/mTOR signaling in tumor cells." (PMID 40867898, 2025). "Therefore, disrupting mTOR by up-regulating LKB1-AMPK signaling is an emerging tumor therapeutic strategy." (PMID 39735555, 2025). "This included MVD and GLUT1 expression in tumors with mutated VHL, mTOR phosphorylation in tumors with activating mutations in PI3K/AKT/mTOR pathway genes, H3K36me3 status and mutations in SETD2 and, lastly, the tumor cell proliferation rate and presence of multiple driver gene mutations." (PMID 40352587, 2025). "They deliver functional miRNAs that modulate tumor signaling pathways: adipose-derived MSC exosomes carrying miR-199a-3p enhance sorafenib sensitivity in HCC cells by suppressing mTOR signaling, while other miRNAs like miR-100 and miR-143 inhibit tumor progression through key regulatory pathways." (PMID 41301162, 2025). "Palmitoylated PD- 1 also activates the mTOR pathway, promoting tumor cell proliferation." (PMID 40335986, 2025). "Additionally, mTOR inhibitors have anti-tumor effects, as the phosphoinositide 3-kinase/protein kinase B (Akt)/mTOR signaling pathway plays a crucial role in regulating cell proliferation and apoptosis." (PMID 40421010, 2025). "By modulating metastatic pathways such as TGF-β, NF-κB, and PI3K/AKT/mTOR signaling, which are involved in tumor progression and metastasis, these combination strategies have the potential to improve clinical outcomes and provide durable responses for OC patients with fewer adverse effects." (PMID 40075635, 2025). "Additionally, trials are investigating agents that target components of the mTOR pathway or related pathways to address tumor escape mechanisms." (PMID 40002868, 2025). "Moreover, the “Warburg effect” in tumor cells is also influenced by the activity of mammalian target of rapamycin (mTOR)." (PMID 40034817, 2025). "Moreover, treatments such as programmed death ligand 1 (PD-L1) blockade can indirectly suppress tumor glycolysis via mTOR inhibition, highlighting the complex interplay between metabolism and immune regulation." (PMID 40658684, 2025). "AMPK activation has important tumor suppressor functions, inhibiting the mTOR pathway for example." (PMID 39955067, 2025). "Studies have demonstrated that oncolytic viruses exert antitumor effects through autophagy in two ways: Firstly, viruses can hinder autophagy-inhibiting signals such as AKT/mTOR, leading to increased autophagosome formation, subsequent membrane damage, and promotion of tumor cell death." (PMID 41377584, 2025). "The PI3K/Akt/mTOR signaling pathway intricately governs tumor cell dormancy." (PMID 41404065, 2025). "On the other hand, the mTOR pathway is crucial for enabling tumor cells to evade the immune system." (PMID 40140647, 2025).
tumor (continued). "Ectopic expression of miR-218 revealed that miR-218 exerted its tumor suppressive effects in OSCC cells by targeting the rapamycin-insensitive component of mTOR or Rictor with consequent inhibition of AKT S473 phosphorylation and inactivation of PI3K/AKT signaling." (PMID 40746882, 2025). "Furthermore, culturing chimeric antigen receptor (CAR) T cells in the presence of PI3K or mTOR inhibitors during ex vivo expansion can improve their metabolic fitness, persistence, and anti-tumor efficacy upon infusion." (PMID 40386392, 2025). "Additionally, mTOR can influence tumor initiation and progression through post-translational modifications, such as phosphorylation." (PMID 40704062, 2025). "Together, these findings provide strong evidence for the tumor-intrinsic molecular alterations induced by the RAC1A159V mutation that promote tumor cell glycolysis, suppress chemokine production, and reduce cell surface IFNGR1 via glycosphingolipid mediated mTOR activation." (PMID 41160695, 2025). "Aberrant signaling of oncogenic pathways (e.g., PI3K/AKT/mTOR pathway) drives tumor progression." (PMID 40129297, 2025). "In addition, the PI3K/AKT/mTOR pathway plays an important role in cell cycle regulation, and both of them jointly promote tumor proliferation." (PMID 41281744, 2025). "When the mTOR pathway is over-activated, it may enhance the survival of tumour cells through a feedback loop, leading to resistance to Temsirolimus." (PMID 40591061, 2025). "In addition, we found that NR6A1 can affect mTOR signaling, suggesting a broader role in tumor metabolism regulation." (PMID 41219936, 2025). "Long-term administration of metformin (250 mg/day) inhibited neoplasia or polyp recurrence, suggesting mTOR inhibition mediated by metformin could suppress protein biosynthesis and proliferation of tumor cells." (PMID 39776799, 2025). "Similarly, targeted therapies, particularly VEGF and mTOR inhibitors, disrupt tumor angiogenesis and key oncogenic pathways but often lead to adaptive resistance, necessitating combination strategies." (PMID 40677703, 2025). "In preclinical RMS studies, mTOR inhibition has reduced cellular migration, invasion, tumor growth, and angiogenesis, suggesting that targeting mTOR could be therapeutically useful." (PMID 40508013, 2025). "Thus, PI3K/mTOR inhibitors like NVP-BEZ235 were shown to inhibit tumor cell proliferation, and further sensitize glioma stem cells to radiotherapy through the activation of autophagy, increased apoptosis, cell cycle arrest and reduced DNA repair." (PMID 40075567, 2025). "Based on our findings, we propose that NR6A1 may orchestrate cellular bioenergetics metabolism across diverse tumor cell types via mTOR signaling." (PMID 41219936, 2025). "The PI3K/AKT/mTOR signaling pathway plays a central role in modulating tumor radioresistance by systematically influencing tumor responses to radiotherapy through mechanisms such as DNA damage repair, cell cycle regulation, and the control of cell proliferation and apoptosis." (PMID 40725100, 2025). "Hence, it remains possible that mTOR inhibition or more specific PIK3CA inhibition would have been able to resensitize the tumor of the presented patient to Infigratinib treatment." (PMID 40260297, 2025). "However, in tumor cells, abnormally activated mTOR sends signals that encourage tumor cells to grow." (PMID 40558273, 2025). "Notably, combining NCAPH knockdown with an mTOR inhibitor (Everolimus) or a cyclin-dependent kinase inhibitor (Flavopiridol) demonstrated promising anti-tumor effects both in vitro and in vivo." (PMID 39991770, 2025).
tumor (continued). "At the molecular level, the anti-apoptotic proteins Bcl-2/Bcl-xl enable tumor cells to evade programmed cell death by suppressing mitochondrial apoptosis, while the Akt/mTOR signaling pathway promotes tumor growth, metabolic reprogramming, and survival signals." (PMID 40363681, 2025). "The protein network between MAPK- and mTOR-signaling pathways is very complex and it may include cross-activation or cross-inhibition between each other, depending on each tumor type." (PMID 40711277, 2025). "In the tumor microenvironment, increased activity of MCT and LDH leads to the excessive accumulation of lactate, which, by inducing lactylation at different sites, enhances the activity of oncogenic pathways such as JAK-STAT and PI3K/Akt/mTOR, thereby accelerating tumor cell invasion." (PMID 40704062, 2025). "Recent studies suggest that mTOR inhibitors such as everolimus may effectively reduce tumor growth in resistant cases.." (PMID 40787520, 2025). "Hypoxia enhances the expression of PD-L1 in tumor cells through the hypoxia-inducible factor 1-alpha (HIF-1α)/mTOR pathway, and activates G protein-coupled receptor (GPR81) through lactic acid, inhibiting the antigen-presenting ability of DCs and forming type I TME, namely “cold tumor” type." (PMID 41281945, 2025). "Therefore, investigating the regulatory mechanisms of the mTOR signaling pathway in tumor glycolysis is essential." (PMID 41219936, 2025). "The antiproliferative effects of the synthesized compounds were confirmed by a reduction in phosphorylated AKT (p-AKT) expression at 10 μM, indicating an impact on the PI3K/AKT/mTOR signaling pathway, which is crucial for cell cycle regulation and tumor progression." (PMID 41537091, 2025). "The findings indicate that abemaciclib, in combination with RT, enhanced tumor cell radiosensitivity, enhanced gamma-H2AX phosphorylation, reduced AKT phosphorylation, attenuated PI3K/mTOR signaling, alleviated radiation-induced vasculogenesis, and enhanced tumor growth delay." (PMID 40035822, 2025). "Its inhibition reduced mTOR phosphorylation and tumor proliferation." (PMID 41458541, 2025). "However, the efficacy of mTOR inhibition as a treatment for tumor-induced neurological dysfunction in humans remains unexplored." (PMID 41301687, 2025). "Briefly, the Janus kinase (JAK)/signal transducer and activator of transcription (STAT)/phosphatidylinositol-3 kinase(PI3k)/protein kinase B (AkT)/mammalian target of rapamycin (mTOR) signaling pathways are overreactive in BC, driving tumor cells’ survival and proliferation." (PMID 41514586, 2025). "Mutations in either the PI3K/AKT/mTOR pathway or the MAPK pathway may induce the dysregulation of signal transduction and alterations in the feedback loop, potentially leading to tumor development." (PMID 40142329, 2025). "The disruption of OIS may suppress the PI3K pathway through PI3K and mTOR, potentially attenuating tumor progression." (PMID 40781676, 2025). "Consequently, a substantial amount of undegraded SLC7A5 is retained in the membrane, which enhances leucine transport, thereby activating the mTOR pathway and ultimately promoting tumor growth." (PMID 41312360, 2025). "Therefore, the findings reveal that QSOX2‐mediated disulfide bond modification enhances tumor stemness by activating mTOR signaling, highlighting a promising therapeutic target in ESCC." (PMID 40433832, 2025). "Moreover, through signaling pathways such as Nrf2, RhoA/ROCK, EGFR/PI3K/Akt, Bax, and PI3K/Akt/mTOR, BJ also suppresses tumor proliferation and metastasis." (PMID 41156537, 2025). "Serine and one-carbon metabolism may serve as key links between mTOR signaling and DNA methylation, promoting tumor growth." (PMID 40265021, 2025). "Furthermore, high expression of neural precursor cell expressed, developmentally downregulated 8 (NEDD8) enhances autophagy activation by inhibiting the PI3K/AKT/mTOR pathway, significantly increasing tumor cell radioresistance." (PMID 40725100, 2025).
tumor (continued). "However, the precise interplay between CQ-mediated mTOR regulation and its chemosensitization efficacy remains incompletely defined, particularly regarding tumor type-specific pathway dependencies." (PMID 40299634, 2025). "Furthermore, sorafenib blocked tumorigenesis of HCCLM3 cells more effectively than that of HCCLM3/mTOR cells, manifesting as reduced tumor volumes and tumor weights, with minimal effects on body weights of nude mice." (PMID 39863613, 2025). "For example, cholesterol depletion mediated by ABCG1 transporter‐dependent reverse transport reduces cholesterol levels in the TME, activating the pathway to increase tumor cell lipogenesis, thereby amplifying PI3K/AKT/mTOR signaling cascades and promoting tumor proliferation." (PMID 40904700, 2025). "While the synergistic inhibition of tumor growth by PI3K/mTOR inhibitor may due to simultaneously disrupts anabolic processes." (PMID 39953539, 2025). "A recent study proposed miR34a as a viable biomarker in the follow-up of ES disease, even though miR-185 was shown to be involved in ES cell proliferation, motility, and survival by downregulating the PI3K/Akt/mTOR and Wnt/β-catenin pathways, which functions as a tumour suppressor." (PMID 39941818, 2025). "However, given the important role of the PI3K/AKT/mTOR pathway in normal cell metabolism, major on-target, off-tumor side effects, particularly hyperglycemia and hyperlipidemia, have impaired wide adaptation of these inhibitors in clinical practice." (PMID 41157306, 2025). "This metabolic reprogramming suppresses antitumor immunity through three interconnected mechanisms: First, competitive glucose uptake by tumor cells and TAMs induces nutrient deprivation in TILs, suppressing mTOR activity and reducing effector cytokine secretion (e.g., IFN-γ, TNF-α)." (PMID 40563359, 2025). "Furthermore, by inhibiting the activation of the Ras/Raf/MEK/ERK/MAPK and PI3K/AKT/mTOR pathways, lactate production, and tumor cell survival can be reduced, enhancing the therapeutic efficacy of ADCs." (PMID 40303296, 2025). "In fact, feeding a reduced protein diet to mice suppresses tumor growth, an effect mediated through both cancer cell intrinsic mechanisms (e.g. reducing insulin-like growth factor 1 signaling and inhibiting mTOR activity), as well as enhancing the anti-tumor immune response." (PMID 40105196, 2025). "Our approach of giving mTOR inhibitors to UC patients might enhance tumor recognition and destruction, potentially improving the overall efficacy of ICI." (PMID 39258533, 2025). "However, GAS5 exerts its tumor-suppressive effects by interacting with the PI3K/AKT/mTOR pathway through the upregulation of PTEN and the direct inhibition of AKT activation." (PMID 40142329, 2025). "Another study showed that LINC00152 promotes HCV-induced carcinogenesis by activating genes involved in cell cycle regulation, proliferation, epithelial–mesenchymal transition, and tumor invasion through modulation of several signaling pathways, including mTOR and EMT." (PMID 41465470, 2025). "A large number of studies have found that autophagy inhibitors target LC3, p62, beclin-1 and autophagy associated gene 5 (Atg5) in conjunction with PTT, while inhibiting the AKT/mTOR signaling pathway, significantly enhancing the autophagy activity in tumor cells." (PMID 40688079, 2025). "Indeed, a similar approach with a static binding algorithm has been conducted with lupeol in the context of intracellular tumor promoting proteins, such as mTOR, topoisomerase, Bcl-2, and PI3K." (PMID 41303616, 2025).
tumor (continued). "PTEN typically suppresses the PI3K/AKT/mTOR signaling pathway, and its absence not only promotes tumor development but also improves immunological checkpoint signaling, thus producing an immunosuppressive environment that permits malignancies to escape immune surveillance." (PMID 40739089, 2025). "It is highly plausible that NR6A1 modulates mTOR activity through altering tumor cell metabolic states, and mTOR may subsequently regulate cellular metabolism and proliferation." (PMID 41219936, 2025). "Conversely, they may be detected in CRC patients whose tumor cells are more sensitive to mechanistic Target of Rapamycin (mTOR) inhibitors, such as everolimus and rapamycin; however, these interactions have only been studied at a clinical trial level." (PMID 40868288, 2025). "Additionally, elevated expression of CCL2 in gefitinib-resistant cell lines facilitates the recruitment of M2-type macrophages and activates the AKT/mTOR signaling pathway, thereby diminishing gefitinib’s anti-tumor efficacy." (PMID 40003951, 2025). "In addition, mTOR expression was higher in DLBCL than non-tumor control samples, and in tumors, mTOR expression was higher in CD86+ cells in the peri-T area." (PMID 41415285, 2025). "mTOR (mammalian target of rapamycin) is involved in many signaling pathways, regulating cell proliferation, autophagy, and apoptosis, and it plays a critical role in tumor metabolism and invasion downstream of AKT." (PMID 40508013, 2025). "Notably, the combination of QSOX2 inhibitor Ebselen, mTOR inhibitor Rapamycin, and chemotherapy effectively inhibits tumor growth, reduces tumor stemness, and induces tumor dormancy in mouse." (PMID 40433832, 2025). "Additional targeted signals were noted for CDK4/6 and mTOR pathways: palbociclib limited proliferation and induced apoptosis via oxidative stress in CC models, and in combination with SHetA2 suppressed phospho-Rb and tumor growth in SiHa xenografts." (PMID 41303721, 2025). "Our observations indicate that medicarpin may inhibit these processes by targeting both upstream and downstream components, including PIK3CA, AKT1, and mTOR, therefore resensitizing tumor cells to apoptotic signals." (PMID 41516052, 2025). "We hypothesized that the combined effect on the PI3K/AKT/mTOR pathway could be synergistic, leading to a more potent inhibition of cell proliferation and survival signals, ultimately resulting in superior tumor control." (PMID 40456804, 2025). "Combination therapies targeting CTLA-4 and metabolic checkpoints such as mTOR inhibitors have shown potential in enhancing anti-tumor immunity and may offer a more effective therapeutic approach for CCA patients." (PMID 41394868, 2025). "Furthermore,through in vitro and in vivo experiments, we demonstrated that anti-tumor metabolites produced by F. rodentium can also modulate PDPN/CLEC-2/PI3K/AKT/mTOR signaling in CRC." (PMID 40693815, 2025). "Additionally, it regulates mammalian target of rapamycin (mTOR signaling), influencing neutrophil metabolism and function within hypoxic tumor regions." (PMID 40486614, 2025). "Furthermore, the effect of mTOR inhibitors on tumor metabolism and angiogenesis has been evaluated using imaging techniques such as positron emission tomography (PET) scans." (PMID 40717210, 2025). "The specific molecular mechanism revealed that PI3Kγ signaling through Akt and mTOR downregulates NFκB activation while stimulating C/EBPβ activation; the latter promotes an immunosuppressive transcriptional program during inflammation and tumor growth." (PMID 40725182, 2025). "Moreover, compared with alisertib-treated mice, the CD45+CD11b+F4/80+ cells in tumor tissue from β-glucan-trained mice showed a higher intracellular phospho-S6, suggesting that AurA inhibition inhibited mTOR activation in TAMs." (PMID 40920087, 2025). "Finally, we investigated the therapeutic potential of shikonin, demonstrating its anti-tumor effects via modulation of the TEK-AKT/mTOR signaling pathways." (PMID 40808675, 2025).